CCL2 (C-C motif chemokine ligand 2)
Diseases named in the same sentence as CCL2 in open-access papers (continued):
Sharing a sentence is not in itself a finding about the gene and the disease.
cancer (continued). "Importantly, in the HIF1A-knockout HepG2 cells, our qRT-PCR data confirmed the selected mRNA changes revealed by RNA-sequencing, and with TCGA pan-cancer data, we revealed that the expressional levels of these three genes, LUM, SCOC, and CCL2, were associated with immune cell infiltration levels." (PMID 35774500, 2022). "Interestingly, while primary carcinoma cells secreted CCL2, matched metastatic lines (i.e., lines from metastatic lesions in the same animals) showed greater mRNA and CCL2 secretion." (PMID 36256464, 2022). "However, iCAFs expressed significantly higher levels of CCL2 than myCAFs, suggesting a hierarchy for recruiting monocyte-derived macrophages to immunosuppressive niches in order of iCAFs > myCAFs > metastatic cells > primary carcinoma cells." (PMID 36256464, 2022). "Thus, the CCL2/CCR2 axis has a critical role in the multiple stages of cancer metastasis." (PMID 34804061, 2021). "Moreover, some reports have revealed that CCL2 impairs cancer immunotherapy, and its blockade might thus be beneficial to the outcome of cancer therapy." (PMID 34593796, 2021). "Finally, conditioning of WT mice with CCL2-conjugated exosomes, followed by injection of syngeneic cancer cells, led to a significant (p < 0.05) increase in lung metastasis formation compared to non-conjugated exosomes, while no impact on BC metastasis was noticed in the lungs of CCR2−/− mice." (PMID 34112803, 2021). "TNF-α expression was observed to upregulate expression of several cancer-associated genes in the epithelial cells which include extracellular matrix (ECM) remodeling genes such as MMP9, PLAU, FN1 and ICAM1, chemokines such as CCL2, CXCL2, CXCL3 and CXCL10 and regulatory genes such as UBD and PTGS2." (PMID 34946170, 2021). "Thus, CCL2 plays an important role in cancer growth, progression, and metastasis in TME." (PMID 34445235, 2021). "CAF-derived CCL2 could induce cancer stem cells by activating NOTCH signaling." (PMID 34804061, 2021). "Melatonin could delay cancer progression by inhibiting CCL2 release from TANs." (PMID 34464477, 2021). "First, we found that expression of CCL-2 was significantly higher in TNFR1 deficient mice, suggesting that tumors developed in those mice exhibit a pronounced infiltration of TAMs, which display a permissive M2-like phenotype, thus promoting angiogenesis, immunosuppression and cancer progression." (PMID 33202705, 2020). "Finally, BRAF mutated cells also have angiogenic capacity, since they can induce other cancer cells and microenvironmental cells to secrete CXCL8 and CCL2, two pro-tumorigenic chemokines, leading to cancer cell proliferation and macrophage-mediated angiogenesis." (PMID 33193402, 2020). "Likewise, ΔNp63 transcriptional factor, which is often up-regulated in cancer cells, could directly induce CCL2 and CCL22 expression and the following metastatic spread by myeloid cell accumulation." (PMID 32133298, 2020). "In addition, biglycan, through interaction with TLR2/4 receptors on the surface of macrophages, promotes inflammation by triggering the synthesis of two cytokines important for cancer progression, TNFα and CCL2, and thus enhances tumor growth in many cancer cells." (PMID 32847060, 2020). "Indeed, cancer cells educate monocytes into M2-like macrophages by releasing C-C motif chemokine ligand 2 which in turn secrete EGF, hence increasing cancer cell motility by mean of invadopodia formation, facilitating tumor local invasion and distant metastasis." (PMID 33178698, 2020). "Senescence-associated secretory phenotype (SASP) is defined by production of CCL2/MCP1, TNFα, IFNγ, IL-6, growth and differentiation factors (TGFβ and HGF), and matrix remodeling enzymes (metalloproteinases; MMP1/3/10/13) and is implicated in cancer growth and organ regeneration." (PMID 30683864, 2019). "Also cancer cells were reported to express CCL2, thereby increasing tumor growth and osteolysis." (PMID 31572390, 2019).
cancer (continued). "Since loss of VHL is found in the majority of sporadic RCC and JunB is up-regulated in the VHL-deficient RCC specimens, these results suggest that CCL2 production by cancer cells via aberrant JunB expression might be a predominant mechanism to enhance TAM accumulation in RCC." (PMID 30483271, 2018). "Therefore, MMP-9, as one of the mediators of the CCL2/CCR2 axis interaction, may cause the inhibition of cancer cell migration and invasion." (PMID 28424406, 2017). "Thus, it is not surprising to observe that an elevated expression of CCL2/CCR2 is present in several cancer types and is associated with adverse clinical outcomes." (PMID 27409666, 2016). "Hence, in addition to leukocytes, CCL2 can also attract cancer cells to secondary sites, although this process is more complex and may require interactions with other hematopoietic cell types." (PMID 26885690, 2016). "However, we demonstrated that CCL2 is localized predominantly to cancer cells in CRCLMs rather than in stroma-associated cells." (PMID 27058904, 2016). "However, the relevance of CCL2 expression to cancer stem cell renewal in TNBC is unclear." (PMID 27283985, 2016). "Thus, it is plausible that CCL2 and/or CCL5 blockade might reduce such immunosuppression and facilitate immunotherapy of HPV associated cancers." (PMID 25340820, 2014). "These associations between therapy resistance and STAT1 in cancer may explain the association of STAT1 levels with higher CCL2 and CXCL10 and the apparent lack of therapy sensitivity in high STAT1 patients." (PMID 24460726, 2014). "Moreover, CCL2 mediates development of the cancer stem cell (CSC) phenotype." (PMID 25165728, 2014). "Among these increased cytokines by AR silencing, CCL2 has drawn our attention since early studies have shown CCL2 could promote cancer metastasis via recruitment of macrophages and the molecular mechanism of AR silencing-induced CCL2 expression remains elusive." (PMID 23982944, 2013). "Thus, from some of the results one could argue that LH may serve as a positive regulator on cancer growth and invasion through overexpression of CCl2 and FOSB." (PMID 21711548, 2011). "Neutrophils are polarized to the N2 TAN phenotype via Notch2–Jagged1 interaction of cancer cells and CAFs, accompanied by increased expression of ARG, C-C motif chemokine ligand 2 (CCL2), CXCR4 and MMP-9." (PMID 41429896, 2025). "The chemokines CCL2 and CCL4 recruit leukocytes to the site of injury or cancer, although IFNγ and its inducible IP-10 activate lymphocytes against infections or tumors." (PMID 40145019, 2025). "PDGF, CD154 and/or CCL2.73–75 Conversely, fibroblasts and macrophages are important sources of CCL2 and HGF,76,77 which act on cancer cells to increase CCR2 and MET signaling during DCIS progression." (PMID 40736024, 2025). "Ovarian cancer-TA-MSCs-derived CCL2 and CCL5 increase IL-6 expression in cancer cells, promoting chemotherapy resistance via PYK2 phosphorylation." (PMID 40676710, 2025). "M2 polarization, enhanced by the CCL2/CCR2 axis, correlates with cancer aggressiveness in DE-DLBCL, presenting a potential therapeutic target." (PMID 40426926, 2025). "The axis CCL2 and its receptor CCR2 has been established as an early marker of diagnosis and prognosis in different types of cancers." (PMID 39305371, 2025). "For example, the cytokine CCL2 is known to recruit and activate myeloid-derived suppressor cells in CRC and other cancers." (PMID 41039118, 2025). "CCL2, also known as monocyte chemoattractant protein 1 (MCP1), is produced not only by various types of cancer cells but also by immunosuppressive cells such as TAMs and myeloid-derived suppressor cells (MDSCs)." (PMID 40806751, 2025). "To investigate the correlation between CCL2/7/8 levels and Sca-1 expression levels, we analyzed TCGA BRCA data and saw a positive correlation between CCL2/7/8 or CXCL1 expression level and LY6E expression in cancer tissues." (PMID 40634316, 2025).
cancer (continued). "CCL2, binding to its receptor C–C chemokine receptor type 2 (CCR2), acts as a chemokine, attracting monocytes during cancer progression." (PMID 39749673, 2025). "In cancer cells, DRP1-mediated mitochondrial fission induces cytosolic mtDNA stress to enhance the CCL2 secretion from cancer cells via the TLR9-mediated NF-κB signaling pathway, which promotes M2 polarization." (PMID 41373022, 2025). "In cancer, activation of the NOTCH signaling pathway increases the production of cytokine IL-1β and chemokine CCL2, which induce inflammation and recruitment of tumor-associated macrophages." (PMID 40863244, 2025). "Among the chemokines, monocyte chemoattractant protein-1 (MCP-1) and chemokine (C-C motif) ligand 2 (CCL2) are particularly relevant for cancer growth and progression." (PMID 41179937, 2025). "CCL2, through its interaction with CCR2, facilitates cancer cell migration and recruits immunosuppressive cells into the TME, fostering cancer progression." (PMID 40568576, 2025). "Hypoxia stimulates the production of multiple migratory factors, including vascular endothelial growth factor (VEGF), C-C motif chemokine ligand 2 (CCL2), CCL5, and CSF-1, by carcinoma and stromal cells." (PMID 41019982, 2025). "For instance, researchers have utilized a 12-gene expression signature (including CCL2, CCL3, CCL4, CCL5, and others) to assess TLS presence across different cancer types." (PMID 39620224, 2024). "CCL2 binds and activates CCR2 to attract monocytes, basophils, and macrophages to infiltrate TME, thereby promoting cancer cell invasion as well as metastasis." (PMID 39595209, 2024). "It has been discovered that the interaction between CCL2 and CCR2 is an important signaling axis in cancer growth." (PMID 39201480, 2024). "Therapeutic inhibition of CCL2/CCR2 axis through NF-κB ablation, abrogates inflammatory monocyte recruitment and TAM infiltration in different mice models of several cancer types such as primary and metastatic breast cancer, HCC and lung cancer." (PMID 38397187, 2024). "Elevated circulating levels of 6 cytokines (PD-L1, CXCL10, HGF, CCL2, MIG, and IL-6) were observed in cancer patients compared with that in healthy volunteers." (PMID 38776028, 2024). "A correlation between the concentration of CCL2, monocytes in the TME, and the suppression of the T-cell response can be observed in various cancer models." (PMID 39882242, 2024). "The chemokine CCL2 and its primary receptor CCR2 have garnered significant attention due to their involvement in cancer development." (PMID 38468260, 2024). "Soluble factors such as cytokines (e.g., VEGF, IL-4, and IL-10), chemokines (CCL2, CCL5, CCL7, and CCL22), and enzymes like COX-2, IDO, and MMPs have a direct effect on the suppression of anti-cancer immune responses." (PMID 39409110, 2024). "Targeting the CCL2/CCR2 axis, which plays a crucial role in recruiting monocytes in various cancer types such as pancreatic cancer, offers a promising therapeutic approach to hinder the recruitment of monocytes from the bone marrow into the bloodstream." (PMID 39195299, 2024). "The monocyte chemoattractant protein 1 (MCP-1), also known as CCL2, is an inflammatory chemokine expressed by fibroblasts, endothelial cells, and cancer cells." (PMID 39409924, 2024). "However, for silvestrol we could show that it potentially strengthens the M2 phenotype by reducing expression of CD206, TREM2 and decreasing the release of pro-inflammatory IL-8 and CCL2, thereby possibly weakening the host’s immune defense against cancer by exhausting CD8+ T cells." (PMID 39518983, 2024). "Chemokine receptors have been targeted in therapeutic strategies, and recent years have seen promising results from CCL2/CCR2 antagonists in treating inflammatory and fibrotic diseases and cancer immunotherapy." (PMID 39850880, 2024).
cancer (continued). "Specifically, cancer and microenvironmental cell-secreted IDO1, IL-10, C-C motif chemokine ligand 2 (CCL2) and transforming growth factor beta (TGF-β) promote the expansion of immunosuppressive Tregs within the GBM TME." (PMID 39406966, 2024). "CCL2 has been found to promote EMT processes and enhance cancer stem cell characteristics in TNBC patients, as well as induce M2-like polarization in resident macrophages." (PMID 39776914, 2024). "In fact, the release of several factors such as M-CSF, CCL2, VEGF, and TGF-β and the expression of surface markers (e.g., glypican-3) on cancer cells are responsible of TAM recruitment and polarization." (PMID 38397187, 2024). "Both MSCs and A431 cells secreted MIF, SERPIN1, IL-8, and CXCL1/GRO⍺, while CCL2 and IL-6 were only found in MSC cultures, and CCL5 and GM-CSF were only detected in cancer cell supernatants." (PMID 38674102, 2024). "MiR-196a promoted cancer progression via ANXA1 and CCL2, however, blocking CCL2 restricted invasion within spheroids." (PMID 38455762, 2024). "Due to their important roles in malignancies, CCL2 and CLL7 have also been thoroughly studied as therapeutic targets in cancer therapy." (PMID 38339377, 2024). "Chemokines and cytokines, such as IL6/IL6R and CCR2/CCL2, serve as fundamental regulators within the TME, which has been firmly established as a pivotal driving force in cancer progression." (PMID 38468260, 2024). "From the perspective of cancer cells, HAT down-regulated the expression of TGF-β, TNF-α, EGF, CCL2, CXCL1, and CXCL12, crucial angiogenic and chemotactic factors for ECs." (PMID 38338342, 2024). "On the other hand, once fully transformed, invasive cancer cells seem to upregulate TGF-α, which augments NI over induction of CCL2 secretion from neurons, which acts upon CCR4 on cancer cells." (PMID 37607005, 2023). "CCL2 and its receptor, CCR5, are shown to be involved in cancer cell proliferation, metastasis, and the formation of an immunosuppressive microenvironment." (PMID 38022682, 2023). "TANs can stimulate the recruitment and activation of T cells in cancer through the production of several mediators, including the chemokines CXCL1, CXCL2, CXCL10, CCL2, and CCL3, respectively." (PMID 37444436, 2023). "Based on the effect of A3 on M2-type macrophage polarization, we believe A3-influenced relevant mediators CCL2 and MMP-9 released by macrophages to inhibit angiogenesis and cancer cell migration." (PMID 36838599, 2023). "Of specific interest to this article, RNA therapeutics are also under development that aim to harmonize hyperinflammation (again in cancer), such as aptamer NOX-A12 and NOX-E36, which disrupt the expression of CXCL12 and CCL2, respectively." (PMID 37109050, 2023). "There are 28 types of chemokines (CCL1-CCL28) belonging to the CC chemokine subfamily, among which CCL2, CCL3, CCL5, CCL15, CCL18 and CCL26 exert some regulatory effects on pathological processes such as TAMs infiltration and polarization in cancer." (PMID 36173487, 2023). "CM contained high levels of CCL2/MCP-1, MMPs, and interleukins which are well known for their impact on other cancer entities." (PMID 37781195, 2023). "Positive correlations of VEGF-A among CCL2, IL-6, and IFN-γ and between IFN-γ and IL-6 were observed in Cancer TIF1-γ-DM patients." (PMID 36357631, 2023). "In fact, MSCs attracted myeloid-derived suppressor cells (MDSCs) in a C-C motif chemokine ligand 2 (CCL2)-dependent mechanism, hence lowering the activity of anti-cancer T cells even further." (PMID 37849741, 2023). "We also show that TGF-α promotes the secretion of CCL2 from DRG neurons, which, in turn, activates the cancer cell cytoskeleton through CCR4, paxillin phosphorylation, and cell protrusion formation." (PMID 37607005, 2023).
cancer (continued). "The combination of HFD plus cancer resulted in increased expression of some cytokines in the OFB (e.g., Ccl2, Ccl4, Cxcr2, Il1b) and decreased expression of others (e.g., Ccr5, Cx3cl1, eNos, Tnfa) as compared to the HFD group alone." (PMID 38264656, 2023). "An increase in the expression of CCL2 and IL8 was observed when cancer cells were cocultured with monocytes." (PMID 37628994, 2023). "Cancer cells secrete cytokines/chemokines, such as IL-10, transforming growth factor beta (TGF-β), and chemokine (C-C motif) ligand 2 (CCL2), which exert immune-suppressive effects and promote the recruitment and activation of suppressive cells." (PMID 37569686, 2023). "The elevated expression of CCL2 and CCL5 is mainly secreted by adipocytes, where cancer-derived exosomal miRNA-155 facilitated the production and secretion of CCL2 and CCL5 from adipocytes by modulating the activation of the SOCS6/STAT3 pathway." (PMID 36593475, 2023). "JAK/STAT and PI3K/AKT signaling pathways are activated during the binding of CCL2 to CCR2, which ultimately leads to an increase in the proliferation of cancer cells." (PMID 37325423, 2023). "Of particular concern is that CCL2, IL-6, and IFN-γ were still significantly increased after Bonferroni correction in the Cancer TIF1-γ-DM group." (PMID 36357631, 2023). "The higher levels of plasma VEGF-A, TNF-α, CCL2, IL-6, and IFN-γ were depicted in the Untreated Cancer TIF1-γ-DM group than in the Non-cancer TIF1-γ-DM group." (PMID 36357631, 2023). "Mechanistically, cancer-cell-derived TGF-α upregulated CCL2 secretion from sensory neurons, which induced hyperphosphorylation of the cytoskeletal protein paxillin via CCR4 on cancer cells." (PMID 37607005, 2023). "Herein, we examined the effects of CVC on the mRNA and protein levels of CCR2, CCL2, VEGF, NF-κB, c-Myc, IL33, and vimentin, which are involved in the progression of cancer." (PMID 37325423, 2023). "The binding of CCL2 to CCR2 promotes the recruitment of macrophages to metastatic sites, thereby accelerating the dissemination and expansion of cancer cells." (PMID 38180104, 2023). "Among these chemokines, CCL2, together with its main receptor, CCR2, can increase cancer progression." (PMID 37325423, 2023). "The ability of plasma VEGF-A, TNF-α, CCL2, IL-6, and IFN-γ levels to distinguish the presence of cancer was evaluated through the area under the curve (AUC) analysis." (PMID 36357631, 2023). "Significantly higher levels of plasma VEGF-A, TNF-α, CCL2, IL-6, and IFN-γ were observed among Cancer TIF1-γ-DM patients, especially among untreated Cancer TIF1-γ-DM patients." (PMID 36357631, 2023). "In tumor‐bearing mice, blockade of CCL2/CCR2 signaling inhibits the recruitment of inflammatory monocytes, delays cancer growth and metastasis, reduces postsurgical recurrence, and enhances survival." (PMID 37706196, 2023). "Plasma CCL2, IL-6, and IFN-γ levels were significantly higher in the Treated Cancer TIF1-γ-DM group than in the Non-cancer TIF1-γ-DM group." (PMID 36357631, 2023). "Various cell types, including DC, endothelial cells, monocytes, macrophages, Th1 cells, basophils, NK cells and various cancer cells express CCR2, which binds to CCL2." (PMID 37170733, 2023). "Some researchers have proven that CCL2 can increase angiogenesis by recruiting TAMs and increasing the expression of VEGF in cancer cells." (PMID 37325423, 2023). "The present study identified VEGF-A, TNF-α, CCL2, IL-6, and IFN-γ as significant potential biomarkers indicating the presence of cancer and demonstrated a more detailed cytokine profile during diagnosis." (PMID 36357631, 2023). "We investigated and observed a positive correlation between VEGF-A and CCL2 levels, VEGF-A and IL-6 levels, VEGF-A and IFN-γ levels, and IL-6 and IFN-γ levels within the Cancer TIF1-γ-DM group." (PMID 36357631, 2023). "Among those downregulated, CXCL1, CCL2, CXCL8, CTGF, LIF, and IL-6 are known to be involved in fibrosis or cancer stroma." (PMID 36289649, 2022).